ST6GALNAC6 (ST6 N-acetylgalactosaminide alpha-2,6-sialyltransferase 6)
Description:
Transfers the sialyl group (N-acetyl-alpha-neuraminyl or NeuAc) from CMP-NeuAc onto glycoproteins and glycolipids, forming an alpha-2,6-linkage. Produces branched type disialyl structures by transfer of a sialyl group onto the GalNAc or GlcNAc residue inside backbone core chains having a terminal sialic acid with an alpha-2,3-linkage on Gal. ST6GalNAcVI prefers glycolipids to glycoproteins, predominantly catalyzing the biosynthesis of ganglioside GD1alpha from GM1b. Besides GMb1, MSGG and other glycolipids, it shows activity towards sialyl Lc4Cer generating disialyl Lc4Cer, which can lead to the synthesis of disialyl Lewis a (Le(a)), suggested to be a cancer-associated antigen. Also has activity toward GD1a and GT1b, and can generate DSGG (disialylgalactosylgloboside) from MSGG (monosialylgalactosylgloboside) (By similarity).
Synonyms: ST6GalNAcVI; SIAT7-F; SIAT7F
Tractability: Antibody: UniProt predicts a signal peptide or a membrane-spanning region.
Gene: Protein-coding gene on chromosome 9 (127,885,321 to 127,906,616, reverse strand). Ensembl gene ENSG00000160408.
Subcellular location: Golgi apparatus membrane
Subcellular location (Human Protein Atlas): Cytosol
Pathways (Reactome):
Metabolism: Glycosphingolipid biosynthesis; Lewis blood group biosynthesis
Metabolism of proteins: Sialic acid metabolism
Gene Ontology:
Molecular function: protein binding; sialyltransferase activity; alpha-N-acetylgalactosaminide alpha-2,6-sialyltransferase activity; alpha-N-acetylneuraminyl-2,3-beta-galactosyl-1,3-N-acetyl-galactosaminide 6-alpha-sialyltransferase activity
Biological process: cell-cell recognition; glycoprotein metabolic process; glycosphingolipid metabolic process; glycosylceramide metabolic process; ganglioside biosynthetic process; glycosphingolipid biosynthetic process; oligosaccharide biosynthetic process; oligosaccharide metabolic process; ceramide metabolic process; glycoprotein biosynthetic process
Cellular component: cytoplasm; Golgi membrane; membrane; plasma membrane
Genetic constraint (gnomAD): Loss-of-function variants: 17 observed, 34.14 expected, observed/expected ratio (o/e) 0.5, 90% interval 0.34 to 0.75. The upper end of that interval is the gene's LOEUF score, 0.75, which puts it in group 3 of 6, group 1 being the genes least tolerant of losing a copy. Missense variants: 366 observed, 478.76 expected, observed/expected ratio (o/e) 0.76, 90% interval 0.7 to 0.83. Synonymous variants: 181 observed, 187.74 expected, observed/expected ratio (o/e) 0.96, 90% interval 0.85 to 1.09.
Homologues: Orthologues: macaque ST6GALNAC6 (99% identical), dog ST6GALNAC6 (96% identical), guinea pig ST6GALNAC6 (92% identical), mouse St6galnac6 (91% identical), chimpanzee ST6GALNAC6 (84% identical), rabbit ST6GALNAC6 (77% identical), rat St6galnac6 (76% identical), tropical clawed frog st6galnac6 (59% identical), zebrafish st6galnac6 (48% identical). Paralogues in human: ST6GALNAC5 (42% identical), ST6GALNAC3 (34% identical), ST6GALNAC4 (33% identical), ST6GAL2 (18% identical), ST3GAL1 (17% identical), ST3GAL2 (17% identical), ST3GAL4 (17% identical), ST3GAL5 (17% identical), ST6GALNAC1 (17% identical), ST6GALNAC2 (16% identical), ST3GAL3 (16% identical), ST3GAL6 (15% identical), and 2 more.
Diseases named in the same sentence as ST6GALNAC6 in open-access papers:
ST6GALNAC6 is named in the same sentence as 7 diseases in open-access papers, as found by Europe PMC text mining. Sharing a sentence is not in itself a finding about the gene and the disease. The quoted sentences say what the papers report.
colon cancer (5 papers, 2020 to 2021). "Such downregulation of ST6GalNAc6 occurs already in early-stage colon cancer and has been associated with epigenetic silencing." (PMID 34975914, 2021). "A study in colon cancer has shown that ST6GALNAC6 is responsible for the synthesis of sialyl Lewis (a), which is a significant inductive mechanism in cancer progression." (PMID 34943806, 2021). "We proposed that this is due to NF-κB-mediated PRC2 epigenetic silencing of SLC26A2 and ST6GalNAc6 during the very early stages of colon cancer." (PMID 32050430, 2020). "In human colon cancer ST6GalNAc6 is downregulated compared to nonmalignant epithelium, which is paralleled by a decrease in disialyl LeA expression and a concomitant increase in sialyl LeA." (PMID 34975914, 2021). "While the tissue and individual levels of each transcript are very heterogeneous, significant cancer-associated differences are not reported, except for ST6GALNAC6 and, paradoxically, B3GALT5, which is dramatically down-regulated in colon cancer." (PMID 32527016, 2020).
colitis (1 paper, 2024). Inflammation of the colon. "Moreover, mice with a B3galt5 missense mutation, which was observed in IBD patients, showed mild spontaneous colitis because of the reduced sialylation of Muc2, similar to St6galnac6-deficient mice." (PMID 39589551, 2024). "Another recent study clearly demonstrated that mice devoid of St6galnac6, which is highly and selectively expressed in mouse colonic epithelia, develop spontaneous colitis because of the less lubricant mucus with the unidirectional Muc2 network structure due to the reduced sialylation." (PMID 39589551, 2024).
lung carcinoma (1 paper, 2022). "Overexpression of ST6GalNAc4 has been crucial for tumor cell glycosylation modification and lung cancer metastasis, although the roles of ST6GalNAc5 and ST6GalNAc6 in malignancies remain unclear." (PMID 36605200, 2022).
renal cell carcinoma (1 paper, 2021). "However, ST6GalNAc6 may also enhance the metastatic capability of tumor cells, as silencing of ST6GalNAc6 in a renal cell carcinoma (RCC) cell line, expressing lower levels of DSGb5, exhibited decreased migration, but not proliferation, in vitro." (PMID 34975914, 2021).
cancer (2 papers, 2021 to 2022). A tumor composed of atypical neoplastic, often pleomorphic cells that invade other tissues. "In contrast, a limited number of genes are predominantly downregulated throughout all cancer types, such as ST6GALNAC6, ST6GALNAC3, GALNT16 and MAN1C1." (PMID 36009354, 2022).
ST6GALNAC6 also shares sentences with these, for which no sentence is quoted: tumor (2 papers); lung adenocarcinoma (1).